MYC (MYC proto-oncogene, bHLH transcription factor)
Diseases named in the same sentence as MYC in open-access papers (continued):
Sharing a sentence is not in itself a finding about the gene and the disease.
infection (continued). "In contrast, loop formation during infection varies with MYC expression, raising the question of whether the changes in flipon conformation induced by MYC and FACT play a role in how the EBV genome folds and which viral genes are expressed." (PMID 35328502, 2022). "Among the highlighted findings were the overrepresentation of purine and pyriminidine biosynthesis, glycolysis and cytoskeleton regulatory pathways during the early phase of infection and an increasing activation of the PPP and MYC with the progression of infection." (PMID 34696497, 2021). "Speculatively, different outcomes of E4orf6 effects on MYC could occur at different stages of infection." (PMID 34066504, 2021). "The transcription factors such as the C2H2 zinc finger, bZIP (basic domain/leucine zipper), WRKY, AP2 (APETALA2)/ERF (ethylene-responsive factor), NAM/ATAF/CUC(NAC), MYB, MYC and bHLH (basic helix–loop–helix), were significantly altered after viroid infection in plants." (PMID 33005494, 2020). "In addition, MYC knockdown decreased viral titre, providing evidence that metabolic changes do indeed enhance virus yield during infection." (PMID 30744016, 2019). "Infection of MYC/Runx2 mice with WT MLV reduced animal survival by 10 days." (PMID 31815961, 2019). "Globally, the infection time course for the IN TP- series showed a biphasic DoD curve, with one-third of the mice developing tumors early, as with WT infection, and two-thirds of the mice developing tumors later, paralleling the uninfected MYC/Runx2 control mice." (PMID 31815961, 2019). "However, key EBNA2, EBNA-LP and MYC target genes important for primary B-cell remodeling and activation remain to be defined in this early period post-infection." (PMID 31518366, 2019). "Moreover, upstream regulator analysis predicted MYC to be activated with time of infection and protein and RNA data for genes controlled by this transcription factor showed good correlation, which validated the use of protein data for this prediction." (PMID 30252905, 2018). "We found that infection with Jad/C(4fC) resulted in the significant upregulation of c-MYC (P < 4 × 10−6), TBX3 (P < 0.0006), AXIN2 (P < 0.0068), FNDC3B (P < 1 × 10−5), FASN (P < 0.0005) and CCND1 (P < 0.0002), with c-MYC and TBX3 showing the highest upregulation levels." (PMID 30046100, 2018). "We used 4C-sequencing to determine whether infection of resting B cells by EBV induced the same changes in MYC enhancer interactions observed in EBV-infected cell lines." (PMID 27490482, 2016). "Therefore, higher MeP-MECP2e2 multiplicity of infection (MOI) was used to obtain MAP2 positive neurons with detectable MYC signals." (PMID 25644311, 2015). "We determined that cis-motifs matching RNFG1, ABRE, GT-1, GCN4, GluB-1, BPBF, WRKY, TATAboxIII, ARF, and MYC were the most abundant cis-elements in the selected OsNAC genes that were differentially expressed during infection with one or more of the viruses (RDV, RBSDV, RGSV, and RRSV)." (PMID 26442000, 2015). "Additionally, we compare AD WT infection to AD ORF1 D68A infection to assess effects of adenovirus-mediated MYC activation on regulation of glutamine metabolism during infection." (PMID 26561297, 2015). "Whether HSV-1, influenza A, or other viruses also rely on MYC activation to promote reprogramming of glutamine metabolism during infection remains to be determined." (PMID 26561297, 2015). "A recent study has shown that MYC expression was induced in primary human blood-derived macrophages following in vitro infection with pathogenic and non-pathogenic mycobacterial species." (PMID 25324841, 2014). "We started with the analysis of the expression pattern of TS, RRM1 and RRM2 (two subunits of RR) in SK-Mel-19 and SK-Mel-29 cells 6 days post-infection with control or MYC shRNAs, i.e. at the time point when the majority of MYC-depleted cells underwent senescence." (PMID 23249808, 2012).
infection (continued). "Importantly these findings are not limited to mouse as the switch to metastasis was also observed in the human NSCLC cell line A-549 upon infection with MYC virus." (PMID 19551151, 2009). "We presume that the need for such infection has been circumvented by overexpression of the MYC transgene, which serves as a surrogate for the translocations that are a hallmark of human BL and are thought to occur subsequent to initiation of tumorigenesis by EBV or another agent." (PMID 18578569, 2008). "A parallel increase in renal c-MYC protein levels was detected in tissue sections from infected Irf3−/− mice, compared to uninfected controls, specifically along the mucosal lining of the renal pelvis and in the renal papillae, which are primary infection sites." (PMID 40000737, 2025). "The c-MYC was over-expressed on REH cells by lentivirus infection and Western blot to verify whether the THZ1-induced reduction of cellular metabolism in B-ALL cells was regulated by c-MYC, and the result confirmed that the mRNA and protein levels of c-MYC were upregulated in REH cells." (PMID 33889549, 2021). "Furthermore, the low activity of MYC at the first infection stage affects the low expression of SLC25A6, which suffers from the repression of human miR1244-1, the transcriptional silence of DNA methylation (p-value = 1.14 × 10−2), and the acetylation by acetyltransferase protein KAT5." (PMID 30133498, 2018). "Our data suggest that the adenovirus-induced increase in glutamine consumption is MYC-dependent since cells infected with a mutant adenovirus deficient in MYC activation, AD ORF1 D68A6, do not exhibit increased glutamine consumption rates at early time points post infection." (PMID 26561297, 2015). "The upregulation of the Wnt target gene expression, including Axin2, EPHB2, CCND1, CD44, TERT, and MYC in PEDV-infected cells, further highlights the activation of WNT signaling in response to infection." (PMID 40396761, 2025). "Increased nucleolar size was observed by two days post-EBV infection of primary human B-cells, which reached peak size at day 4 post-infection, a time-point where there are highly elevated levels of EBNA2 and MYC." (PMID 40367275, 2025). "TRP120-mediated degradation leads to upregulation of oncoproteins (c-MYC, NICD,c-Jun and MCL1) during infection." (PMID 40028182, 2025). "As for some DZ signature genes, the LZ biomarker CD83 is downregulated upon infection in ensemble experiments but retained in EBV+ subsets co-expressing BCL2A1 (BFL-1) and other GC LZ hallmarks (CD80, CD86, and MYC)." (PMID 38059622, 2024). "We then transduced the same MYC:CTRL or PKR constructs as above in NoDice∆PKR FHA:Dicer N1 cells and performed the same analysis after infection with SINV-GFP." (PMID 38287188, 2024). "The list of transcription factors modulated by the infection includes the IRF, MYC-MAX, NFY, and E2F families; RELA; YY1; CREB1; and others." (PMID 37998351, 2023). "In this study, genes involved in JA/ET signaling and biosynthesis, such as LOX, AOS, MYC, and ERF were induced, and the JA content significantly increased during infection." (PMID 36008749, 2022). "Some upstream regulators were common between both parasite stages (MYC, KLF4, and SMAD3) albeit with variations in the number and/or identity of downstream targets in each type of infection." (PMID 35430587, 2022). "Only infection by B95.8 induced MYC, a well characterized regulator of metabolism, as well as CTPS1 by 48 h of infection." (PMID 34281398, 2021). "DDR1 expression in SW620 cells increased the transcript levels of MYC, FRA1, and JUN compared with control (mock infection)." (PMID 29438985, 2018). "Upregulation of MYC by EBNA2 plays a key role in stimulating B-cell proliferation early in infection, promoting immortalisation." (PMID 27490482, 2016). "The final network is centered around the MYC transcription factor, which was up-regulated in CA04 infections, and enriched for ‘Cell Growth and Proliferation’ (P-value = 2.0E-6)." (PMID 22937776, 2012).
infection (continued). "New insights are gained into the precise modulation of MYC and IFN‐γ activity in SV/HLHS, which may help balance immune responses and reduce harmful inflammation, and promote effective tissue repair and infection control." (PMID 40831036, 2025). "At a high dose of C. neoformans at the same timepoint, we did not observe MYC targets; however, there was increased expression of genes involved in protein secretion, potentially upregulating cytokine release in response to infection." (PMID 40985448, 2025). "According to this mechanism, MYC translocation (and thus MYC deregulation) will occur stochastically at one or a few cells that will express more CR2 in its membrane, which in turn will lead to a more efficient infection." (PMID 39766110, 2024). "Thus, it can be assumed that VV-GMCSF-Lact infection proceeds with the suppression of E2F and NFY, while the decrease in MYC-MAX and E2F activity is directly related to the increase in viral transcripts." (PMID 37998351, 2023). "This increased consumption was abrogated by shRNA knockdown of MYC, or infection with the non-MYC binding E4ORF1-D68A mutant adenovirus." (PMID 30744016, 2019). "P3HR-1 infection failed to upregulate ACC1, FASN or EBNA2 target MYC, as did infection with UV-irradiated B95-8, which can enter cells but does not induce EBV-encoded genes." (PMID 31518366, 2019). "For host interactions, MRPL50 via C. albicans WO-1 infection directly triggers TF FOXA1 but not protein MYC (also knowns C-Myc) in C. albicans SC5314 infection." (PMID 30769958, 2019). "On the contrary, the expression of the MYC-branch representative gene VSP2 was not significantly affected by the infection neither in the WT plants nor in the mutant." (PMID 31611892, 2019). "At 2 days after infection, EBV markedly induced expression of MYC, CD21, CD23, HES1, and BATF (positive controls) 10- to 20-fold, possibly through EBNA2; in contrast, host housekeeping genes including β-2 microglobulin (B2M) and RNA polymerase II (POLR2A) were unaffected." (PMID 30487153, 2018). "At the first stage of infection, SLC25A6, which has low acetylation activity and DNA methylation activity (p-value = 1.14 × 10−2), is repressed by human miR1244-1 and reduces transcriptional regulation via TFs, ESR1 and MYC." (PMID 30133498, 2018). "These experiments revealed that infection with a “wild type” EBV modestly induced p16INK4a transcription in the first few days after infection – when EBNA2 transactivates inducers of cell cycle progression (e.g., MYC and cyclin D2) and a period of hyperproliferation has been described." (PMID 24167519, 2013). "The deoxyribonucleosides were added next day after infection with MYC shRNA, and culture media with and without deoxyribonucleosides were refreshed every 2 days." (PMID 23249808, 2012). "Metastatic conversion by c-MYC can be reconstructed in cell culture by using non-metastatic A-549 NSCLC cells and infection with a MYC transducing retrovirus." (PMID 19551151, 2009). "Precisely modulating MYC and IFN‐γ activity in SV/HLHS, based on the insights gained from our study, may balance immune responses, reduce harmful inflammation, and promote effective tissue repair and infection control." (PMID 40831036, 2025). "The overwhelming majority of changed miRNAs were downregulated after infection and infection plus SP-A2 (1A0) protein rescue, and these were predicted to target genes that play a role in cell cycle and growth and proliferation pathways, such as CCND1, CCND2, CDK7, CDKN2A, E2F1, E2F2, E2F3, and MYC." (PMID 35844510, 2022). "However, in response to infection, male mice exhibited higher expression levels of CDKN1B, and CTNNB1 (KO, 1A3), TCF4 (1A0, 6A2), TAP1, and TAP2, (1A0), CDKN1A, (1A3, 6A2), MARCO, and MMP12 (1A3), CCND1, CDK2, IRF and MYC (6A2) compared to females." (PMID 32670284, 2020). "Thus, at the first stage of infection, the low activity of genes miR185 and MYC results in a lack of pro-apoptotic activity." (PMID 30133498, 2018).
infection (continued). "First, pig iPSCs could be induced by KLF4, SOX2, and MYC (but not OCT4) infection, although transgenes were not silenced." (PMID 27336671, 2016). "After infection with H. pylori strains, qRT-PCR results indicated a significant decrease of mRNA expression of CCND1 (p < 0.001 for both J166 and 7.13 strains) and c-MYC (p < 0.01 and p < 0.001 for J166 and 7.13 strains, respectively) in TFF1 expressing cells as compared to control cells." (PMID 25980439, 2015). "However, the lack of an overt phenotype in our model under normal physiological conditions in the absence of infection or tissue damage suggests that growth during normal tissue homeostasis in at least some adult tissues does not linearly respond to changes in MYC levels." (PMID 28583252, 2017). "The knockdown of MYC revealed a strong negative effect on growth, with a relative decrease in GFP positive cells of more than 40% in most cell lines at day 22 after infection." (PMID 35205272, 2022).
hematological malignancies (88 papers, 2012 to 2026). "This study is aimed at assessing diagnostic and prognostic value of plasma c-MYC expression to aid in early diagnosis and prognosis of hematological malignancies." (PMID 38223598, 2023). "High c-MYC levels have been associated with the susceptibility of hematological malignancies to inhibition of mitochondrial protein synthesis." (PMID 37973789, 2023). "The proto-oncogene c-MYC has been linked to carcinogenesis, particularly in hematological malignancies." (PMID 37627164, 2023). "In summary, this study suggests the suitability of plasma c-MYC as a promising screening tool for populations at risk of hematological malignancies." (PMID 38223598, 2023). "In particular, different types of hematological malignancies and their association with MYC deregulation have been thoroughly discussed in this review along with the effects of various MYC inhibitors." (PMID 34372899, 2021). "In some hematological malignancies, MYC is frequently subject to missense mutations that enhance its transformation activity." (PMID 34885204, 2021). "Numerous studies support the complementary role of CEBPA and c-MYC transcription factors in risk stratification of hematologic malignancies development." (PMID 33170359, 2020). "To a certain extent, we can consider that MYC-mediated transcriptional amplification or activation through SEs is an important hallmark of hematologic malignancies." (PMID 31311566, 2019). "Specifically, BRD4 has been shown to associate with the MYC gene in hematological malignancies and drive MYC expression." (PMID 25537515, 2015). "Notably, CCDC26 overlaps the BENC (blood enhancer cluster), a distal regulatory element that physically contacts the MYC promoter and is implicated in MYC activation via enhancer hijacking mechanisms in multiple hematologic malignancies." (PMID 41509392, 2025). "Plasma c-MYC ratio showed promising screening/diagnostic value for hematological malignancies." (PMID 38223598, 2023). "While efforts to target MYC have been largely unsuccessful, the novel triazolothienodiazepine BET inhibitor OTX015 (MK-8628) has shown potent preclinical antitumor activity in hematologic malignancies as well as in several solid tumors, in association with down-regulated MYC expression." (PMID 27935867, 2017). "By targeting a central regulator of transcriptional elongation, this approach selectively disrupts the sustained expression of survival-critical proteins such as MCL-1 and MYC, thereby exposing a therapeutic vulnerability in hematologic malignancies." (PMID 42201387, 2026). "This review focuses primarily on hematologic malignancies because they exhibit pronounced transcriptional addiction to short-lived super-enhancer-driven transcripts (MYC, MCL-1), making CDK9 inhibition particularly effective." (PMID 42201387, 2026). "Our data support the model that HPV+ HNSCC exhibits a form of viral enhancer-addiction, analogous to the super-enhancer dependency described in MYC-driven hematological malignancies." (PMID 41323280, 2025). "The effects of CDK9 have been studied in hematologic malignancies, and many of them have suggested the downregulation of master transcription factor MYC or upregulation of anti-apoptotic molecules such as MCL1 and BCL2." (PMID 40713627, 2025). "In summary, as our understanding of MYC biology has increased and immunotherapeutic strategies, such as immune checkpoint blockade, have demonstrated clinical efficacy in treating hematologic malignancies, we have positive hopes for the future." (PMID 40732268, 2025). "Due to their close proximity at the 8q24 locus, PVT1 and the oncogene MYC are often considered twin players and a positive interaction feedback loop has been demonstrated in other hematological malignancies." (PMID 40721648, 2025). "APTO253, originally described as a MYC inhibitor is a drug developed for the clinical treatment of hematological malignancies." (PMID 37143070, 2023).